IRF1 (interferon regulatory factor 1)
Diseases named in the same sentence as IRF1 in open-access papers (continued):
Sharing a sentence is not in itself a finding about the gene and the disease.
inflammatory bowel disease (9 papers, 2009 to 2025). A spectrum of small and large bowel inflammatory diseases of unknown etiology. "Thus, IRF-1 signaling may also be implicated in progression and aggravation of inflammatory bowel diseases by supporting the accumulation of dysregulated NCR+ ILCs, which has been reported in the inflamed gut mucosa in CD43,44." (PMID 36175404, 2022). "We discovered an inflammatory bowel disease (IBD) GWAS variant rs17622517 that affects the expression of the transcription factor IRF1 in cis under early immune stimulus, and a large number of genes in trans under late stimulus." (PMID 34314424, 2021). "Several IEC signature TFs have known associations with human Inflammatory Bowel Diseases (IBD), including SMAD7, CEBPG, STAT3, XBP1, HNF4A, ELF3, IRF1, and NFκB components IKBKB, IKBKG, and NFKBIZ." (PMID 28850571, 2017). "IRF1, IRF8, and STAT1 are important in human inflammatory diseases including systemic sclerosis, systemic lupus erythematosus, and inflammatory bowel disease." (PMID 36091020, 2022). "Studies have demonstrated that IRF1 is associated with Behcet’s disease whereas IRF5 has been found to be associated with certain autoimmune diseases such as systemic lupus erythematosus (SLE), inflammatory bowel disease (IBD), rheumatoid arthritis (RA), and multiple sclerosis (MS)." (PMID 19816589, 2009). "IRF1 upregulates multiple PANoptosome components, including ZBP1, RIPK1, and AIM2, driving PANoptosis in models of inflammatory bowel disease (IBD) and alcoholic liver disease." (PMID 41583472, 2025). "Interestingly, in a mouse model of inflammatory bowel disease, Carinh has been reported to physically interact with p300/CBP, transcriptional co-activators that can bind to a wide set of transcription factors to enhance the expression of numerous target genes, including, but not limited to, Irf1." (PMID 39773901, 2025).
lung adenocarcinoma (9 papers, 2013 to 2025). A carcinoma that arises from the lung and is characterized by the presence of malignant glandular epithelial cells. "Utilizing IL-2 successfully counteracts the inhibitory impact of elevated IRF1 expression on the proliferation, migration, and invasion of lung adenocarcinoma cells." (PMID 38915471, 2024). "Similarly, another study showed that overexpression of PSAT1 promotes the metastasis of lung adenocarcinoma via the inhibition of STAT1 as well as its downstream targets, IRF1 and IFNG." (PMID 40298450, 2025). "Although STAT1 and STAT2 activate IRF1, the protein level of IRF1 was not correlated with that of STAT2 in all the tissues and had a significant correlation with that of STAT1 only in the normal tissue of lung adenocarcinoma." (PMID 30305853, 2018). "Our results suggest that overexpression of HMGA1, E2F6, IRF1, and TFDP1 and downregulation or no expression of SUV39H1, RBL1, and HNRPD in blood is suitable for diagnosis of lung adenocarcinoma and squamous cell carcinoma sub-types of NSCLC." (PMID 24564251, 2013).
systemic lupus erythematosus (9 papers, 2009 to 2025). An autoimmune multi-organ disease typically associated with vasculopathy and autoantibody production. "The importance to precisely control IRF1 levels and its functional output is underpinned by the fact that aberrant IRF1 expression is linked to inflammatory syndromes, such as Behcet’s disease, arthritis, and systemic lupus erythematosus." (PMID 37622993, 2023). "Upregulated IRF1 was shown to contribute to the inflammasome hyperactivity associated to systemic lupus erythematosus, while an IFN-κ-driven keratinocyte-mediated autocrine loop was recently proposed as the pathogenic initiator of cutaneous lupus erythematosus." (PMID 30200670, 2018). "While IRF1, IRF3, IRF5, and IRF8 predominantly exacerbate AS, context-dependent roles (e.g., IRF5 in lupus-associated AS) highlight their therapeutic complexity." (PMID 40980176, 2025). "Our study showed that expression of the Irf1 gene was lower in both the liver and spleen from the spermidine-treated group compared to the lupus control group, which expands the anti-inflammatory effect of spermidine in SLE." (PMID 39337408, 2024). "This revealed that three prioritised lupus genes (USP18, STAT1, IFNA1-17) were shared with the 13 category I genes (IFNAR1/2 signal transduction proteins) and four prioritised genes (IRF1/5/8 and OAS1) were shared with the 38 category II genes (transcriptional targets of interferon response)." (PMID 41038828, 2025).
metastatic melanoma (8 papers, 2015 to 2025). A melanoma that has spread from its primary site to another anatomic site. "Higher IRF-1 expression in tumor tissue has been correlated with longer progression-free survival (PFS) in metastatic melanoma patients treated with CPIs." (PMID 30400835, 2018). "Upon further investigation of the JAK/STAT pathway, we found that metastatic melanoma cells lack the interferon response factor IRF-1." (PMID 25690042, 2015). "By activating STAT1/IRF1 signaling through IFN-γ in tumor-associated macrophages, SP140 promotes PD-L1 expression, which has been reported as both a therapeutic target and a predictive biomarker of immunotherapy response in cancers such as metastatic melanoma and head and neck neoplasms." (PMID 41188771, 2025). "In summary, this study reports the promising association of individual immunotherapy panel markers CD274, PDCD1LG2, CD8A, IRF1 and a combined L1/L2 score (CD274 & PDCD1LG2) with improved immunotherapy outcome in metastatic melanoma." (PMID 31533832, 2019).
tuberculosis (8 papers, 2009 to 2025). A chronic, recurrent infection caused by the bacterium Mycobacterium tuberculosis. "The diagnostic potential of CD274, IRF1 and HPSE in active tuberculosis (ATB) is supported by their strong positive correlation with neutrophil infiltration, as shown in validation datasets (GSE62525 and GSE28623)." (PMID 40607433, 2025). "The experimental results showed that IRF1 was up‐regulated in tuberculosis group, which was consistent with the results of our bioinformatics analysis." (PMID 34213077, 2021). "IRF1 DNA binding was also enhanced in macrophages ex vivo infected with Mycobacterium tuberculosis, and IRF1 mRNA expression was elevated in bronchoalveolair lavage samples of tuberculosis patients compared to samples of healthy volunteers." (PMID 31178872, 2019). "Genes encoding IRF1 and IRF8 protein have been proposed as candidate tuberculosis susceptibility genes." (PMID 22879909, 2012). "Moreover, miR-23a-3p was shown to inhibit monocyte function and phagocytosis by targeting IRF1/SP1 followed by the TLR4/TNF-α/TGF-β1/IL-10 signaling pathway in patients with active tuberculosis." (PMID 34608568, 2021). "This shows that IRF1 is a key gene in the occurrence and development of tuberculosis." (PMID 34213077, 2021). "IRF1 may be used as a biomarker for the diagnosis of tuberculosis." (PMID 34213077, 2021). "None of the seven tagSNPs was individually associated with tuberculosis in the IRF1 gene." (PMID 22879909, 2012). "In order to elucidate whether the IRF1 and IRF8 variants were associated with tuberculosis susceptibility, we conducted a case-control study consisting of 495 controls and 452 ethnically matched cases with tuberculosis in a Chinese population." (PMID 22879909, 2012). "In order to investigate the mechanisms of these responses, we used nebulized rIFN-γ1b in eleven drug-sensitive tuberculosis patients, and found an increase in signaling molecules STAT-1, IRF-1 and IRF-9." (PMID 19753300, 2009). "Chromatin immunoprecipitation and RNA sequencing studies of genes bound and activated by IRF8, IRF1, PU.1, and STAT1, revealed the existence of an IRF1/IRF8 regulome, which plays critical roles in inflammatory and antimicrobial defense, such as neuroinflammation and tuberculosis." (PMID 31178872, 2019).
acute coronary syndrome (7 papers, 2022 to 2025). Signs and symptoms related to acute ischemia of the myocardium secondary to coronary artery disease. "A previous study investigated how interferon regulatory factor-1 (IRF-1) facilitates macrophage scorching among patients with acute coronary syndrome, and elevated m6A and METTL3 levels were observed in macrophages." (PMID 38562618, 2024). "This work extends previous research and implicates down-regulating METTL3 or adjusting IRF-1 as a targeted therapy for the prevention and treatment of acute coronary syndrome." (PMID 38988324, 2024). "A study discovered that interferon regulatory factor-1 (IRF-1) can effectually promote macrophage pyrolysis in the patients with acute coronary syndrome (ACS)." (PMID 36178367, 2022). "Previous study investigated the manner by which interferon regulatory factor-1 (IRF-1) can promote the pyroptosis of macrophages in patients with acute coronary syndrome and detected increased levels of m6A and METTL3 in the macrophages." (PMID 35141221, 2022). "Recent research has revealed that METTL3 up-regulates m6A levels of circ_0029589 with the reader protein YTHDF2, reduces circ_0029589 expression, and mediates IFN regulatory factor 1 (IRF-1) pro-macrophage pyroptosis and inflammation in acute coronary syndrome." (PMID 38988324, 2024). "IRF1-driven IFN-γ/TNF-α production contributes to plaque rupture and acute coronary syndromes (ACS)." (PMID 40980176, 2025). "In DCs in acute coronary syndrome(ACS) patients, IRF1 overexpression enhances lectin-like LOX-1 expression, promoting oxLDL binding and internalization." (PMID 40980176, 2025). "In acute coronary syndrome (ACS), the overexpression or inhibition of IRF-1 effectively modulated caspase-1 activation, macrophage lysis and GSDMD expression, suggesting that IRF-1 potently activates ox-LDL-induced macrophage pyroptosis." (PMID 36544106, 2022). "The overexpression of IRF-1 can induce an increase in the levels of m6A and METTL3 to promote acute coronary syndrome." (PMID 35141221, 2022). "IRF-1 overexpression increases m6A and METTL3 levels and promotes acute coronary syndrome." (PMID 38562618, 2024).
breast tumors (7 papers, 2011 to 2025). "Therefore, differential induction of anti-apoptotic genes directly by NF-kB and pro-apoptotic genes through NF-kB target IRF1, may determine ER+ breast tumor predisposition to succumb or resist endocrine therapy." (PMID 26460486, 2015). "The IRF1 pleiotropic activity is indicated by the increased expression of IRF1 in HER2+ breast tumor basal cells that in contrast to FB2 cells, were associated with the IL6-JAK-STAT3 signaling pathway." (PMID 40862725, 2025). "The IRF1/autophagy-related gene−7 (ATG7) signaling pathway is also key to tamoxifen resistance in estrogen receptor-positive (ER+) breast tumors." (PMID 36226063, 2022). "Protein expression studies show that in breast tumors the most prevalent location of IRF1 is within the cytosol (90%); this location suggests a transcriptionally inactive form of IRF1." (PMID 22295238, 2011). "An acquired resistance model involving aromatase inhibitors shows that IRF1 expression is reduced in long-term estrogen deprived MCF7 cells, indicating IRF1 is a key gene that is consistently reduced in AE resistant breast tumors." (PMID 22295238, 2011). "Furthermore, immunohistochemistry detections confirmed that Dp administration decreased the level of p-Akt and promoted IRF1 in xenografted breast tumors in vivo." (PMID 27388461, 2016). "Our results from mechanistic studies in HMEC, gene expression analysis of ER+/HER2- tumors from the TCGA cohort and analysis of ER+/HER2- breast tumors by IHC implicate basal activity of RelA in suppressing proliferation through upregulation of IRF1 and downregulation of CDK4." (PMID 26460486, 2015). "Expression of IRF1 in murine breast tumor cells promotes apoptosis and inhibits tumor growth." (PMID 26460486, 2015). "IRF1 expression in ER+ breast tumors negatively correlates with tumor grade." (PMID 26460486, 2015). "Thus, some breast tumors may differentially regulate the activation of IRF1 by controlling its subcellular localization." (PMID 22295238, 2011). "In agreement with its role in immune cell function, RNASET2 was downregulated or absent in EPI2 epithelial cell cluster in HER2+ breast tumors, as seen for the expression pattern of IRF1." (PMID 40862725, 2025). "To further examine the role of ID4 in cancer stemness, we knocked down ID4 in MDA-MB-468 breast tumor cells using SMARTpool siRNAs, and tested the expression of a panel of stemness genes including Twist1, Twist2, Snail, Slug, BMP2, IRF1, SOX4, Foxk1 and Notch3." (PMID 36291790, 2022).
cutaneous melanoma (7 papers, 2018 to 2025). A primary melanoma arising from atypical melanocytes in the skin. "In a retrospective study, higher expression of Irf1 and interferon response genes correlated with more favorable prognosis in patients with cutaneous melanoma." (PMID 31507609, 2019). "The transcript expression of STAT1, STAT3, and IRF1, three key transcription factors of the IFNγ signaling cascade, were also lower in the TCGA UVM dataset compared to the TCGA cutaneous melanomas." (PMID 29977240, 2018).
influenza (7 papers, 2015 to 2022). An acute viral infection of the respiratory tract, occurring in isolated cases, in epidemics, or in pandemics; it is caused by serologically different strains of viruses (influenzaviruses) designated A, B, and C, has a 3-day incubation period, and usually lasts for 3 to 10 days. "IRF-1 regulates ZBP1 in the NLRP3 inflammasome, leading to cell death during influenza infection, but a direct link between IRF-1 and cell death during SARS-CoV-2 infection has not yet been established." (PMID 35244141, 2022). "Parallel findings were observed in antigen-specific cells 1 week post-influenza X31-OVA infection, including differences in motifs for BORIS, IRF1, and TCF1 in WT compared to Pik3cdE1020K/+ cells." (PMID 34644563, 2021).
malaria (7 papers, 2009 to 2016). Malaria is a serious and sometimes fatal disease caused by a parasite that commonly infects a certain type of mosquito which feeds on humans. "Our finding are consistent with a previously reported association between polymorphisms in the IRF1 and the control of P. falciparum infection both in healthy adults and children displaying severe and uncomplicated malaria." (PMID 22615793, 2012). "Other cytokine-related findings include one SNP (rs2706384) in the Interferon Regulatory Factor 1 gene (IRF1), which was associated with an increased risk for clinical malaria." (PMID 22615793, 2012). "We have genotyped 18 Single Nucleotide Polymorphisms (SNPs) in the IRF1 genetic region in 961 nuclear trios comprising one child affected by severe malaria and his/her two parents." (PMID 19145247, 2009). "It is therefore possible that IRF1 functional variants with an effect on malaria susceptibility/resistance exist in the Fula and Mossi populations of Burkina Faso but not in the study populations presented here." (PMID 19145247, 2009). "We have shown that IRF1 polymorphisms are associated with the control of P. falciparum infection (parasite prevalence and density), both in healthy adult subjects and in children with uncomplicated and severe malaria." (PMID 19145247, 2009). "The effects of IRF1 polymorphisms on severe malaria may be too small to be detected with this sample size, or may affect only a sub-phenotype of severe malaria." (PMID 19145247, 2009). "In order to investigate whether genetic variation at the IRF1 locus contributes to a child's risk of developing severe malaria, we conducted a large multi-centre association study." (PMID 19145247, 2009). "Furthermore, the effects of IRF1 polymorphisms on severe malaria may be too small to be detected with this sample size, or may affect only a sub-phenotype of severe malaria." (PMID 24312262, 2013). "In the present study we investigated whether genetic variation at the IRF1 locus affects susceptibility to severe malaria by performing a family based association test in nuclear trios consisting of an affected child and his/her two parents from The Gambia, Kenya and Malawi." (PMID 19145247, 2009). "This is also consistent with linkage analyses in mice and genetic studies in humans showing an association of IL3, IL4, IL13, IRF1, and ARHGAP26 with parasitaemia, mild malaria or severe malaria." (PMID 24884991, 2014). "Here we assess the role of IRF1 genetic variation in severe malaria, and by considering multiple populations, we able to investigate regional differences, whilst standardizing phenotype definition and study design." (PMID 19145247, 2009). "Our data demonstrate the first evidence that polymorphisms in IL17 may be associated with uncomplicated malaria in the Cameroonian population while SNPs in, IL10, IL17RD, IRF1, TLR1and TLR9 may be linked with severe malaria in general." (PMID 24312262, 2013). "Since the transcription factor IRF1 is a critical effector molecule in IFN-gamma signalling, variants may affect human susceptibility to malaria." (PMID 24312262, 2013). "Our data demonstrate the first evidence that polymorphisms inIL17 may be associated with uncomplicated malaria in the Cameroonian population while SNPs in, IL10 IL17RD, IRF1, TLR1 and TLR9 may be linked with severe malaria." (PMID 24312262, 2013). "We have previously investigated the role of the transcription factor IRF-1, a critical effector molecule in IFN-gamma signalling, in susceptibility to malaria by conducting genetic association studies in Burkina Faso based on cross-sectional parasitological surveys and case-control clinical studies." (PMID 19145247, 2009). "In contrast, many macrophage inhibition-related genes were up-regulated after malaria, including haem oxygenase 1 (HMOX1), JunB, and IRF1." (PMID 24188121, 2013).
osteosarcoma (7 papers, 2020 to 2025). A usually aggressive malignant bone-forming mesenchymal neoplasm, predominantly affecting adolescents and young adults. "This downregulation of IRF1 contributes to enhanced cell proliferation, migration, and invasion in Osteosarcoma cells." (PMID 40429954, 2025). "For example, extremely radioresistant osteosarcomas were shown to exhibit significantly reduced IRF1 expression levels." (PMID 35436994, 2022).
periodontitis (7 papers, 2017 to 2025). An acute or chronic inflammatory process that affects the tissues that surround and support the teeth. "A significant reduction of the IRF-1 mRNA expression was also associated with DS patients compared to euploid individuals affected by periodontitis." (PMID 28748038, 2017). "Likewise, lower expression of STAT1 (p < 0.02) and interferon regulatory factor 1 (IRF1) (p < 0.01) was identified compared to euploid controls with periodontitis." (PMID 41462866, 2025). "Downregulation of tumor suppressor genes including IRF1, LDOC1, and FOXO3 was also evident in tissues from patients with chronic periodontitis." (PMID 40924302, 2025). "The machine-learning method, RF, was performed to create an ideal model to predict the occurrence of periodontitis and selected five hub PRGs (CHMP2B, GZMB, ZBP1, IL1B, and IRF1)." (PMID 37090158, 2023). "Interestingly, in patients with T2DM who are known to have a higher susceptibility to periodontitis, we observed a heterogenous reprogramming of circulating intermediate and non-classical monocytes toward M1 transcription activation, including an increase in STAT1, IRF1 in intermediate monocytes." (PMID 32210958, 2020). "The analysis of gingival tissue samples from patients with DS and periodontitis showed attenuated expression of signal transducer and activator of transcription 1 (STAT1) and IFN regulatory factor 1 (IRF1) genes, confirming an altered activation of IFN signaling." (PMID 34200970, 2021).